ITM2A (integral membrane protein 2A)
Synonyms: BRICD2A; E25A
Tractability: Antibody: UniProt predicts a signal peptide or a membrane-spanning region; its Gene Ontology location is reachable by antibodies, with medium confidence; the Human Protein Atlas places it where antibodies can reach. PROTAC: ubiquitination databases record sites on it.
Gene: Protein-coding gene on chromosome X (79,360,384 to 79,367,697, reverse strand). Ensembl gene ENSG00000078596.
Subcellular location: Membrane
Subcellular location (Human Protein Atlas): Vesicles; Golgi apparatus; Plasma membrane
Gene Ontology:
Molecular function: protein binding; amyloid-beta binding
Biological process: negative regulation of amyloid precursor protein biosynthetic process
Cellular component: Golgi apparatus; plasma membrane; membrane
Homologues: Orthologues: chimpanzee ITM2A (100% identical), macaque ITM2A (100% identical), rabbit ITM2A (98% identical), mouse Itm2a (95% identical), rat Itm2a (94% identical), pig ITM2A (92% identical), tropical clawed frog itm2a (57% identical), Drosophila melanogaster CG3662 (24% identical), Caenorhabditis elegans itm-2 (19% identical). Paralogues in human: ITM2B (41% identical), ITM2C (37% identical).
Diseases named in the same sentence as ITM2A in open-access papers:
ITM2A is named in the same sentence as 45 diseases in open-access papers, as found by Europe PMC text mining. Sharing a sentence is not in itself a finding about the gene and the disease. The quoted sentences say what the papers report.
breast cancer (11 papers, 2019 to 2025). A primary or metastatic malignant neoplasm involving the breast. "This analysis identified ITM2A, a gene expressed at low levels in breast cancer tissues and associated with prognosis in triple-negative breast cancer patients." (PMID 40657365, 2025). "High expression of integral membrane protein 2A (ITM2A) was reported to be associated with favorable prognosis in several solid tumors including breast cancer." (PMID 33680917, 2020). "The DEGs in breast cancer cells overexpressed ITM2A were found to be associated with immunity responses." (PMID 33680917, 2020). "This provoked our concentration on the association between ITM2A and tumor immunity in breast cancer." (PMID 33680917, 2020). "In summary, we identified significantly down-regulated expression of ITM2A that was associated with poor prognosis in human breast cancer patients, especially in HER2-E subtype breast cancer patients, through bioinformatics analysis." (PMID 31438969, 2019). "Although we demonstrated the tumor suppression role of ITM2A in human breast cancer patients, more future studies are needed to underline the roles of the HUNK/ITM2A axis." (PMID 31438969, 2019). "The AE (for Nm, ERm and AE: p < 0.0001, HR = 0.75, 95% CI = 0.68–0.82) and MR (for Nm, ERm and MR: p < 0.0001, HR = 0.70, 95% CI = 0.62–0.80) data indicated that low ITM2A expression is associated with poor prognosis for breast cancer." (PMID 31438969, 2019). "Our data suggest that ITM2A could be a valuable prognostic marker and promising diagnostic and therapeutic target for breast cancer in the future." (PMID 31438969, 2019). "Other members of the ITM protein family, like ITM2A, have been studied, and it was found that it acts as a tumor suppressor gene in breast cancer." (PMID 37895185, 2023). "A recent study revealed that ITM2A acts as a tumor suppressor in many epithelial cancers, including breast cancer, ovarian cancer, and cervical cancer." (PMID 34872446, 2021). "In summary, we found that high expression of ITM2A reduced the aggressivity of breast cancer cells and had a favorable effect on outcomes of patients with breast cancer." (PMID 33680917, 2020). "This study aimed to investigate the role of ITM2A in breast cancer, especially in respect to tumor microenvironment." (PMID 33680917, 2020). "To validate the inhibitory proliferation in breast cancer cells with ITM2A overexpression in the long term, we then seeded cells transfected with plasmid into 6-well plates and counted the number of clones 14 days later." (PMID 33680917, 2020). "Meanwhile, the correlation on expression levels between PD-L1 and ITM2A was tested via qRT-PCR on 24 breast cancer tissues, as well as public database." (PMID 33680917, 2020). "Collectively, high expression of ITM2A in breast cancer was accompanied with high intensity of TILs and abundant PD-L1 expression." (PMID 33680917, 2020). "Consistent to this point, our study demonstrated that upregulation of ITM2A reduced the aggressivity of breast cancer cells." (PMID 33680917, 2020). "In summary, we found that ITM2A played a tumor suppressor role in breast cancer aggressivity, and had favorable effects on outcomes of patients with breast cancer." (PMID 33680917, 2020). "To explore how the ITM2A expression influence the breast cancer growth in vivo, we then planted MCF-7 cells that transfected with OE-ITM2A or empty vector under axilla of female BALB/c null mice." (PMID 33680917, 2020). "In order to understand the biological role of ITM2A in breast cancer cells, we performed RNA sequencing (RNA-seq) on MCF-7 cells that transfected with OE-ITM2A plasmid or vectors." (PMID 33680917, 2020). "ITM2A inhibited breast cancer cells growth in vitro and in vivo, and reduced the aggressivity of breast cancer via impairing its immigratory and invading capacity." (PMID 33680917, 2020). "The down regulation of ITM2A in breast cancer tissues was further verified in GEO and TCGA datasets." (PMID 33680917, 2020).
breast cancer (continued). "Meanwhile, ITM2A induced PD-L1 expression in breast cancer cells while accompanied with higher TILs numbers in the tumor microenvironment." (PMID 33680917, 2020). "For example, in human breast cancer, autophagy induction is enhanced via cell growth suppression by integral membrane protein 2A PAQR3 inhibits tumor progression in NSCLC cells by modulating EGFR-regulated autophagy." (PMID 33381557, 2020). "ITM2A expression was evaluated based on qRT-PCR results on breast cancer specimens, as well as TCGA and GEO datasets." (PMID 33680917, 2020). "Another study demonstrated that ITM2A inhibited breast cancer cells growth via enhancing autophagy induction through a mTOR-dependent manner." (PMID 33680917, 2020). "First, we analyzed ITM2A expression in collected specimens and found that ITM2A was decreased in breast cancer compared to normal tissues." (PMID 33680917, 2020). "The influence of ITM2A expression on breast cancer cell proliferation and tumor growth were evaluated by CCK-8 assay, clonogenic assay, and murine xenograft models." (PMID 33680917, 2020). "In the present study, we extend and highlight the role of ITM2A in breast cancer via regulation of autophagy." (PMID 31438969, 2019). "We also linked the protein phosphorylation modification of ITM2A by HUNK, a serine/threonine kinase significantly connected with human breast cancer overall survival and HER2-induced mammary tumorigenesis." (PMID 31438969, 2019). "We found that breast cancer patients with low ITM2A expression exhibit poor overall survival and that overexpression of ITM2A significantly inhibits breast cancer cell proliferation." (PMID 31438969, 2019). "Through genome-wide expression analysis, we found that the mRNA level of ITM2A was 7.40-fold down-regulated in breast cancer tissues (n = 1101) compared with that in normal tissues (n = 139) from the TCGA database of breast cancer." (PMID 31438969, 2019). "We also confirmed that ITM2A expression retarded growth and reduced colony formation in breast cancer." (PMID 31438969, 2019). "We next verified the expression of ITM2A in a panel of human breast cancer cell lines, including MCF-7, MDA-MB-231, MDA-MB-468, BT474 and SKBR-3, and the normal breast epithelial cell line Hs578Bst, as well as the human embryonic kidney cell line HEK293T." (PMID 31438969, 2019). "Using the optimal threshold value of 0.863, the sensitivity and specificity values were 0.890 and 0.028, respectively, to identify a patient with breast cancer, indicating that ITM2A serves as an excellent breast cancer marker." (PMID 31438969, 2019). "MTT assay, EdU incorporation assay and colony formation assay were used to evaluated the role of ITM2A on breast cancer cell proliferation." (PMID 31438969, 2019). "Simultaneously, the Kaplan-Meier analysis showed that lowered expression of ITM2A exhibits poor outcomes in breast cancer patients." (PMID 31438969, 2019). "In this study, we also highlight the tumor suppression role of autophagy, particularly ITM2A overexpression induced autophagy, in breast cancer proliferation." (PMID 31438969, 2019). "Western blotting analysis revealed a similar decrease in ITM2A expression in human breast cancer cell lines." (PMID 31438969, 2019). "Our data showed that the expression of integral membrane protein 2A (ITM2A) was significantly down-regulated in human breast cancer tissues and cell lines." (PMID 31438969, 2019). "Immunohistochemical (IHC) analysis also revealed that ITM2A expression levels were significantly decreased in the advanced stages of breast cancer compared to those in adjacent normal tissues." (PMID 31438969, 2019). "We also confirmed the biological role of ITM2A in human breast cancer cells of promoting autophagy and that HUNK phosphorylated ITM2A at T35." (PMID 31438969, 2019). "Through genome-wide expression analysis, we found that the mRNA level of ITM2A was 7.40-fold down-regulated in breast cancer tissues compared with the level in normal tissues." (PMID 31438969, 2019).
breast cancer (continued). "We next investigated the relevance of the ITM2A expression level to the clinicopathological features of breast cancer patients from the TCGA database." (PMID 31438969, 2019). "Besides this, ID4, SEMA3F, FOXD, KCNK5, WNK4 and ECM1 associate with chemoresistance origin and SOX5, ITM2A, SNCG, EPHA4, NTS, FGFR2 and ENPEP associate moreover with breast cancer tumorigenesis." (PMID 37239828, 2023). "Previous studies have shown the suppressor role of ITM2A in ovarian cancer and breast cancer." (PMID 34872446, 2021). "In addition, this correlation was verified by qRT-PCR, which quantified the relative expression levels of ITM2A and PD-L1 of 24 breast cancer specimens." (PMID 33680917, 2020). "Now we concentrate on the biological functions that ITM2A performs in breast cancer." (PMID 33680917, 2020). "We demonstrated that ITM2A was frequently downregulated in breast cancer." (PMID 33680917, 2020). "We then evaluated the prognostic value of ITM2A mRNA in patients with breast cancer." (PMID 33680917, 2020). "Additionally, it was found that breast cancer had higher ITM2A expression frequently had more tumor-infiltrating lymphocytes (TILs)." (PMID 33680917, 2020). "At the same time ITM2A had the ability to promote apoptosis in breast cancer cells." (PMID 33680917, 2020). "It was confirmed that ITM2A was decreased in breast cancer tissues." (PMID 33680917, 2020). "Our study demonstrated the positive correlation between ITM2A expression and TILs in breast cancer." (PMID 33680917, 2020). "Moreover, ITM2A induced PD-L1 expression in breast cancer cells was accompanied with higher TILs numbers in tumor microenvironment." (PMID 33680917, 2020). "Additionally, it was observed that ITM2A not only positively correlated with intensity of TILs and PD-L1 expression but also stimulated expression of PD-L1, PD-L2, and B7-H3 in breast cancer cells." (PMID 33680917, 2020). "Our findings demonstrated that ITM2A could inhibit the migration and invasion of breast cancer cells." (PMID 33680917, 2020). "Survival analysis of ITM2A mRNA in breast cancer patients (the PrognoScan database)." (PMID 33680917, 2020). "In this study, we explored the roles that ITM2A played in breast cancer." (PMID 33680917, 2020). "Meanwhile, RNA-sequencing (RNA-seq) of breast cancer cells that overexpressed ITM2A was conducted." (PMID 33680917, 2020). "In this study, we explored if ITM2A could influence the proliferation and aggressivity of breast cancer cells." (PMID 33680917, 2020). "To test the effect of ITM2A on autophagy flux in breast cancer cells, we detected the protein levels of LC3-II and p62 through western blotting assays, autophagic vacuoles by electron microscopy, and the autolysosome formation using the tandem reporter mRFP-GFP-LC3." (PMID 31438969, 2019). "We next set out to identify the prognostic potential of ITM2A expression in breast cancer patients and to investigate whether ITM2A expression is related to breast cancer patient outcome." (PMID 31438969, 2019). "The results showed a lowered expression of ITM2A in human breast cancer cell lines." (PMID 31438969, 2019). "Taken together, these data indicated that ITM2A promotes autophagy flux in breast cancer cells." (PMID 31438969, 2019). "According to our findings, which showed a significant prognostic effect of ITM2A in HER2-E subtype breast cancer patients, it presents huge possibility that HUNK could phosphorylate ITM2A." (PMID 31438969, 2019). "ITM2A overexpression significantly inhibited the proliferation of breast cancer cells." (PMID 31438969, 2019).
breast cancer (continued). "Furthermore, we generated receiver operating characteristic (ROC) curves and found that the ITM2A mRNA level in breast cancer tissues substantially differs from that in normal tissues, with an area under the curve (AUC) value of 0.935 (95% CI: 0.923–0.948)." (PMID 31438969, 2019). "As ITM2A is downregulated in breast cancer, the inhibitory effect of ITM2A to mTOR could be abolished." (PMID 31438969, 2019). "Indeed, ITM2A has been shown to regulate autophagy in a context-dependent manner: in breast cancer cells, it enhances mTOR-dependent autophagy to inhibit tumor growth, whereas in HEK293 cells, its overexpression disrupts vacuolar ATP synthase and blocks autophagic flux." (PMID 41199749, 2025). "Moreover, ITM2A was found to facilitate breast cancer cells to express PD-L1." (PMID 33680917, 2020). "Thus, we focused on the role of ITM2A in breast cancer on context of immunity." (PMID 33680917, 2020). "However, the biological role of ITM2A in breast cancer remains largely unclear." (PMID 31438969, 2019). "We then replaced T35 with alanine (A) to generate a nonphosphorylatable mutation of the ITM2A protein and texted whether T35 contributed to autophagy induction in human breast cancer cells." (PMID 31438969, 2019). "A comprehensive analysis of data from the TCGA, GEO, and other multicenter cohorts has revealed that ITM2A exhibits distinct low expression patterns in TNBC tissues, which is notably lower compared with other breast cancer subtypes (p<0.001)." (PMID 40657365, 2025). "ITM2A (integral membrane protein 2A) regulates cellular growth and survival, and its low expression may play a role in the progression of BC, especially at advanced stages and higher grades of triple-negative breast cancer." (PMID 37370847, 2023). "ITM2A, as a member of the Type II Integral Membrane protein (ITM2) family, has been reported to exert a tumor suppressor role in breast cancer and ovarian cancer." (PMID 34872446, 2021). "Integral membrane protein 2A (ITM2A), a member of the Type II Integral Membrane protein (ITM2) family, has been reported to act as a tumor suppressor in breast cancer and ovarian cancer." (PMID 34872446, 2021). "Three of the proteins identified as HUNK substrates; EGFR, Run domain Beclin-1-interacting and cysteine-rich domain-containing protein (RUBICON), and integral membrane protein 2A (ITM2A), are described in the context of breast cancer." (PMID 32676513, 2020). "Importantly, we confirmed that ITM2A could stimulate PD-L1 expression in breast cancer cells." (PMID 33680917, 2020). "A positive correlation ranged from intermediate to high between ITM2A and CD8+ T cells was frequently observed over all subtypes of breast cancer." (PMID 33680917, 2020). "To investigate the role of ITM2A in the proliferation of breast cancer cells, we generated the growth curve of MDA-MB-231 cells after ITM2A overexpression using 3-[4,5-dime-thylthiazol-2-yl]-2,5 diphenyl tetrazolium bromide (MTT) assays." (PMID 31438969, 2019). "By studying several autophagic markers and events in human breast cancer SKBR-3 cells, we further demonstrated that ITM2A is a novel positive regulator of autophagy through an mTOR-dependent manner." (PMID 31438969, 2019). "Moreover, we found that ITM2A was phosphorylated at T35 by HUNK, a serine/threonine kinase significantly correlated with human breast cancer overall survival and HER2-induced mammary tumorigenesis." (PMID 31438969, 2019). "However, the biological role of ITM2A in breast cancer has never been elucidated." (PMID 31438969, 2019). "We demonstrated that ITM2A expression significantly correlates with PR status, but not with ER status and HER2 level, suggesting that it could be more effective to use hormone therapy for breast cancer patients with PR positive status and low ITM2A expression." (PMID 31438969, 2019).
ovarian carcinoma (10 papers, 2017 to 2024). A malignant neoplasm originating from the surface ovarian epithelium. "Recent studies, however, have highlighted ITM2A tumor-suppressive effects in various cancer types, including breast and ovarian cancers." (PMID 39766038, 2024). "The expression of ITM2A induced G2/M cell cycle arrest and inhibited ovarian cancer cell growth by decreasing the expression of cyclin B1, p-CDC2, CDC2, and CDC25C." (PMID 32300605, 2020). "In addition, ITM2A deficiency was associated with chemoresistance, including PTX and carboplatin, and ITM2A negatively regulated the IC50 of PTX and carboplatin in ovarian cancer." (PMID 34872446, 2021). "In addition, the loss of ITM2A was significantly correlated with higher FIGO stage, recurrence, chemoresistance, and poorer prognosis in ovarian cancer." (PMID 32300605, 2020). "Additionally, ITM2A was observed to be decreased in acute myeloid leukemia, cervical cancer, and ovarian cancer." (PMID 33680917, 2020). "ITM2A also acts as a tumor suppressor of ovarian cancer via G2/M cell cycle arrest." (PMID 32631357, 2020). "A previous study found that ITM2A could inhibit ovarian cancer growth and induce G2/M cell cycle arrest, indicating that ITM2A was a novel tumor suppressor in ovarian cancer." (PMID 33680917, 2020). "Recently, ITM2A has been identified as a novel tumor suppressor in epithelial ovarian cancer." (PMID 31438969, 2019). "ITM2A has been identified to related to ovarian cancer progress recently." (PMID 31438969, 2019). "Recently, the role of ITM2A in epithelial ovarian cancer has been identified." (PMID 31438969, 2019). "ITM2A is a poorly prognostic biomarker through inducing cell cycle arrest for ovarian cancer." (PMID 29158988, 2017). "ITM2A, a family member of BRICHOS, has been reported to be downregulated in both breast and ovarian cancers which may affect the proliferation and autophagy process of tumors." (PMID 33376725, 2020).